ZNG1E (Zn regulated GTPase metalloprotein activator 1E)
Description:
Zinc chaperone that directly transfers zinc cofactor to target metalloproteins, thereby activating them. Catalyzes zinc insertion into the active site of methionine aminopeptidase METAP1, which function to cleave the initiator methionine from polypeptides during or after protein translation. Mechanistically, the N-terminal psi-PxLVp motif binds to the C6H2-type zinc finger of inactive form of METAP1. After formation of the docked complex, zinc is transferred from the CXCC motif in the GTPase domain of ZNG1E to the zinc binding site in the peptidase domain of METAP1 in a process requiring GTP hydrolysis. GTP/GDP exchange is required for release of active METAP1.
Synonyms: CBWD5; CBWD3; DC36
Tractability: Antibody: the Human Protein Atlas places it where antibodies can reach. PROTAC: ubiquitination databases record sites on it.
Gene: Protein-coding gene on chromosome 9 (65,668,805 to 65,735,823, forward strand). Ensembl gene ENSG00000147996.
Subcellular location: Nucleus
Subcellular location (Human Protein Atlas): Plasma membrane
Gene Ontology:
Molecular function: GTPase activity; zinc chaperone activity; zinc ion binding
Biological process: protein maturation
Cellular component: nucleus
Genetic constraint (gnomAD): Loss-of-function variants: 2 observed, 17.36 expected, observed/expected ratio (o/e) 0.12, 90% interval 0.046 to 0.36. The synonymous counts are far from expectation, so gnomAD's model fits this gene poorly and the ratio says little. Missense variants: 19 observed, 132.36 expected, observed/expected ratio (o/e) 0.14, 90% interval 0.099 to 0.21. Synonymous variants: 9 observed, 41.44 expected, observed/expected ratio (o/e) 0.22, 90% interval 0.13 to 0.38.
Homologues: Orthologues: macaque ZNG1 (98% identical), dog ZNG1 (90% identical), mouse Zng1 (80% identical), rat Zng1a (79% identical), tropical clawed frog zng1b (67% identical), zebrafish cbwd (66% identical). Paralogues in human: ZNG1C (99% identical), ZNG1F (99% identical), ZNG1A (98% identical), ZNG1B (98% identical).
Diseases named in the same sentence as ZNG1E in open-access papers:
ZNG1E is named in the same sentence as 1 disease in open-access papers, as found by Europe PMC text mining. Sharing a sentence is not in itself a finding about the gene and the disease.
ZNG1E shares sentences with these, for which no sentence is quoted: alcoholic fatty liver disease (1 paper).